PDGFRA (platelet derived growth factor receptor alpha)
Diseases named in the same sentence as PDGFRA in open-access papers (continued):
Sharing a sentence is not in itself a finding about the gene and the disease.
metastatic disease (18 papers, 2009 to 2025). "Two of the five patients that were diagnosed with high risk or metastatic disease and the primary resistance mutation PDGFRA p.D842V received imatinib therapy." (PMID 33909171, 2021). "Although numbers were limited, patients with metastatic disease and PDGFRA mutations had a poor OS compared to the remaining metastatic disease patients." (PMID 33909171, 2021). "C-KIT and PDGFRα mutations were detected in 27 out of 40 (67.5%) patients, 17 patients of which were with localized disease and 10 patients with metastatic disease." (PMID 31827510, 2019). "Approximately 85–90% of GISTs harboring KIT or PDGFRA mutations benefit from imatinib treatment before or after surgery and in the setting of unresectable/metastatic disease, except specific mutation such as PDGFRA exon 18 D842V." (PMID 29868467, 2018). "Patient 5 had somatic mutations in HRAS p.G13C, CASP8 p.R127* and PDGFRA p.R764H at all sub-sites in primary and metastatic tumor samples again consistent with these being truncal events." (PMID 27034009, 2016). "These phenotypic changes observed in vitro parallel those findings documented in clinical studies of PTC specimens whereby PDGFRα is strongly associated with metastatic disease." (PMID 27845909, 2016). "A plethora of evidence shows that the MB cells with abnormal PDGFR signaling, attributable to the over-expression of PDGFRs or their ligands, or mutation in PDGFRα, are linked to metastatic disease." (PMID 25576913, 2015). "Several groups have identified specific mutational subtypes in KIT exon 11 associated with an increased risk of metastatic disease whereas GISTs with PDGFRA mutations often behave less aggressive." (PMID 20598160, 2010). "PDGFRA mutations were associated with a poor OS in metastatic disease cases." (PMID 33909171, 2021). "Deletions of dystrophin in KIT/PDGFRA mutant GIST have been previously reported and usually are associated with more advanced clinical stages of disease such as metastatic tumors." (PMID 29510530, 2018). "The controversy regarding the roles of PDGFRα and PDGFRβ in MB has continued, i.e., PDGFRα was deregulated in both the primary and metastatic tumors in a sleeping beauty mouse model of MB." (PMID 25576913, 2015). "Our study confirms the presence of DMD deletions only in KIT/PDGFRA mutant GIST and this event is almost associated with metastatic disease." (PMID 25143820, 2014). "Patients with unresectable tumours or with metastatic disease are treated with Kit/PDGFRA tyrosine kinase inhibitors." (PMID 20062725, 2009). "The proportion of PDGFRA+ fibroblasts was significantly reduced in primary and lymph node metastatic tumors, whereas PSOTN+ and RGS5+ cells were significantly increased compared with adjacent normal tissues, reflecting the general remodeling of extracellular stroma in tumor tissues." (PMID 34185421, 2021). "In general, 81% of the patients with high risk or metastatic disease, without adverse characteristics like comorbidities, too high tumor load or the PDGFRA p.D842V resistance mutation, received imatinib therapy." (PMID 33909171, 2021). "11% (17/159) of the cases with high risk or metastatic disease were not eligible for imatinib therapy due to comorbidity, patients’ refusal, too high tumor load or presence of the PDGFRA p.D842V imatinib-resistance mutation." (PMID 33909171, 2021). "Identification of a distinctive molecular signature involving KIT or PDGFRA mutations allowed targeted therapies in patients with metastatic disease, who did not have effective therapeutic options until then." (PMID 20470368, 2010). "Studies have shown that PDGFRA activates the EMT pathway and decreases the expression of genes that favor epithelial integrity, enhancing metastatic diseases." (PMID 35212838, 2022).
metastatic disease (continued). "We demonstrate that specific blockade of PDGFRα is sufficient to reverse the aggressive phenotypic changes seen in PTC cells and this may represent an advance in therapy for those patients with progressive, metastatic disease." (PMID 27845909, 2016).
oligodendroglioma (18 papers, 2013 to 2025). A well-differentiated (WHO grade II), diffusely infiltrating neuroglial tumor, typically located in the cerebral hemispheres. "PDGFRA amplification is tightly associated with the oligodendroglioma phenotype and data from the TCGA indicate that overexpression and/or amplification of PDGFRA in GBMs is typical of the proneural expression class." (PMID 24236209, 2013). "PDGFRA was diffusely expressed in 100% of oligodendroglioma and meningioma (2.4/4 and 2.2/4 average intensity) and 70‐80% of other tumors at high intensity." (PMID 39473196, 2024). "NG2/CSPG4, PDGFRα, Olig2, Sox10, and Nkx2.2 were preferentially found in human diffuse gliomas with oligodendroglioma or oligoastrocytoma morphology." (PMID 30213051, 2018). "PDGFRs have been found to be overexpressed in human malignant astrocytomas; moreover, expression of NG2/CSPG4 and PDGFRα was identified in oligodendrogliomas, pilocytic astrocytomas and, heterogeneously, in GBs." (PMID 30213051, 2018). "Pathways with enrichment specific to oligodendrogliomas included WNT and beta-catenin signaling, and PDGFRA signaling (PDGFRA amplification is frequent in oligodendrogliomas)." (PMID 29109450, 2017). "Based on aCGH and exome sequencing data, the PDGFRA gene on 4q was neither amplified nor mutated, as is known to happen in high grade oligodendroglioma." (PMID 23527265, 2013). "One of the key regulators of oligodendroglioma development is the PDGFRA pathway." (PMID 23527265, 2013). "However, no variant or amplification was found in PDGFRα on 4q, a gene involved in the development of human oligodendroglioma, or in CDKN2A on 9p, one of the most frequently altered genes in diverse cancer types." (PMID 31217899, 2019). "In our study, no specific genotype was associated with oligodendrogliomas exhibiting T2FMM, but PDGFRA and CCL2 were significantly upregulated among oligodendrogliomas without the sign, which likely reflects sampling bias of inclusion of more HGO in the group without the T2FMM sign." (PMID 37246729, 2023). "Using volcano plot analyses, 2 DEGs, PDGFRA and CCL2 were identified between dogs with and without the T2FMM, both of which were upregulated in dogs with oligodendrogliomas without the T2FMM." (PMID 37246729, 2023). "Oligodendrogliomas exhibit a proneural genetic signature and the OG cells expressed NG2 and PDGFRα; however, they did not express the proneural markers Sox2, CD133, or Olig2 and only expressed low levels of Notch1 and nestin." (PMID 24278309, 2013).
prostate carcinoma (18 papers, 2011 to 2024). A carcinoma that arises from epithelial cells of the prostate gland. "Alterations in PDGFRA, including mutations and amplifications, are frequently found in colorectal, liver, lung, and prostate cancers." (PMID 39594421, 2024). "Additionally, EGFR and PDGFRA mutations were observed in liver, lung, colorectal, and prostate cancers." (PMID 39594421, 2024). "MiR‐491‐5p was also reported to have a negative effect on the regulation of cell proliferation and motility by targeting PDGFRA in prostate cancer." (PMID 33605506, 2021). "In a prostate cancer xenograft model, targeting PDGFRα with olaratumab delayed the progression of early skeletal metastatic foci and reduced the size of skeletal tumors." (PMID 28817103, 2017). "In prostate cancer, metastatic potential of tumor cells is related to PDGFRα expression and PDGF-D overexpression is known to be involved in epithelial-mesenchymal transition." (PMID 24709958, 2014). "For example, HOXC6, a homeobox transcription factor, regulates the expression of genes including BMP7, FGFR2, IGFP3 and PDGFRA to influence oncogenic activities in prostate cancer." (PMID 24009521, 2013). "In a preclinical model of disseminated prostate cancer, it was shown that treatment with a neutralizing antibody against PDGFRα inhibited the growth of skeletal metastases." (PMID 24359404, 2013). "Moreover, siRNA-mediated knockdown of PDGFRα and PDGFRβ suppresses prostate cancer cell growth by the suppression of angiogenesis in a prostate cancer xenograft model." (PMID 28817103, 2017). "In addition, PDGFRα is related to tumor aggressiveness and poor prognosis in breast and prostate cancer." (PMID 24709958, 2014). "Moreover, knock-down of PDGFRα, as well as PDGFRβ, by siRNA suppressed growth of prostate cancer cells in mice and suppressed tumor angiogenesis." (PMID 24359404, 2013). "Elevated levels of PDGF-Aand PDGFRα proteins have also been observed in human prostate carcinomas." (PMID 21559523, 2011). "Importantly, scRNAseq has revealed a highly abundant subpopulation of CAFs present during multiple stages of prostate cancer that express PDGFRα, suggesting that their lineage may trace back to progenitor mesenchymal cells." (PMID 36671452, 2022). "Cell Senescence caused the differential expression of six genes belonging to the KEGG Pathway Prostate Cancer (PDGFRB, PDGFRA, CCNE2, E2F2, EGFR and ZEB1)." (PMID 35205253, 2022). "PDGFRA and PDGFRB were targeted by multiple drugs, and imatinib, a BCR-ABL inhibitor, was identified to target both PDGFRA and PDGFRB in S:E fusion-positive prostate cancer." (PMID 36579559, 2022). "Specifically, half of the “prostate cancer” pathway DEGsSD had previously been referred to in the literature (AR, CDKN1A, CTNNB1, EGFR, KLK2, NKX3-1, PDGFRA, SRD5A2)." (PMID 34768937, 2021). "This suggests that PDGFRA and PDGFRB might be effective therapeutic targets, and imatinib could be a potential candidate drug for S:E fusion-positive prostate cancer." (PMID 36579559, 2022). "PDGFRA and PDGFRB are genes involved in the focal adhesion kinase (FAK)/PI3K-Akt signaling pathway, JAK-STAT pathway, and receptor tyrosine kinase/PDGF signaling pathway in S:E fusion-positive prostate cancer." (PMID 36579559, 2022). "In addition, imatinib, targeting PDGFRA and PDGFRB, was suggested as a potent actionable drug specific for S:E fusion-positive prostate cancer." (PMID 36579559, 2022). "Furthermore, PDGFRα and FSP1 fibroblast markers are also highly expressed in multiple CAF subpopulations identified in prostate cancer (discussed in Section 3)." (PMID 36671452, 2022). "Furthermore, half of the “prostate cancer” pathway DEGsSD are well described in the PCa literature (AR, CDKN1A, CTNNB1, EGFR, KLK2, NKX3-1, PDGFRA, SRD5A2), confirming that this is a pivotal pathway to specifically target clinical questions on canine PCa." (PMID 34768937, 2021).
prostate carcinoma (continued). "Finally, the “prostate cancer” pathway also includes DEGsSD that are relatively specific to the (human) prostate (SRD5A2, KLK2, NKX3-1 and CREB3L4), proto-oncogenes (EGFR, PDGFRA, PDGFRB, NRAS) and druggable candidates (PIK3CD, CTNNB1, PIK3CG, CDKN1A)." (PMID 34768937, 2021). "A prostate cancer related module was investigated (due to its significant enrichment on KEGG prostate cancer pathway), which has DEGs as PDGFRB, PDGFB, SNX2, EGFR and DECGs as (PDGFRA, PDGFRB), (SNX4, PDGFRB), (PDGFB, PDGFRA), (SNX2, PDGFRA), (PDGFRB, PIK3R2), (EGFR, PIK3R2), (EGFR, AREG)." (PMID 26070628, 2015). "The “prostate cancer” pathway also comprises genes that are relatively specific to the (human) prostate (CREB3L4, KLK2, NKX3-1 and SRD5A2), proto-oncogenes (EGFR, NRAS, PDGFRA and PDGFRB), and druggable candidates (CDKN1A, CTNNB1, EGFR, NRAS, PDGFRA, PDGFRB, PIK3CD and PIK3CG)." (PMID 34768937, 2021). "Interestingly, evidence have been presented that a soluble component of the bone marrow can activate PDGFRα, and promote bone metastasis of prostate cancer cells, through a mechanism that does not require ligand-binding or receptor dimerization." (PMID 24359404, 2013).
Stroke (17 papers, 2012 to 2025). Sudden impairment of blood flow to a part of the brain due to occlusion or rupture of an artery to the brain. "Further, longitudinal intravital 2-photon imaging revealed that inhibition of PDGFRα dampened the biphasic pattern of stroke-induced vascular leakage and enhanced vascular perfusion in the ischemic lesion." (PMID 39808499, 2025). "Specific inhibition of PDGF-CC/PDGFRα signaling reduces stroke lesion volume and myofibroblast expansion in the fibrotic scar." (PMID 39808499, 2025). "Our data implicate the PDGF-CC/PDGFRα pathway as a crucial mediator modulating post-stroke pathology and suggest a post-acute treatment opportunity for patients with ischemic stroke targeting myofibroblast expansion to foster long-term CNS repair." (PMID 39808499, 2025). "Residual stroke-responsive PDGFRα+ OPCs were present at 28 days post-stroke in animals on HFD compared with those on CFD (adjusted p = 0.0114)." (PMID 36543124, 2022). "We have also shown that targeting PDGFRα signalling with imatinib reduces stroke volume and BBB disruption after MCAO in mice." (PMID 33361796, 2020). "OPC differentiation following focal white matter stroke is impaired in obese mice, while their platelet-derived growth factor receptor alpha (PDGFRα)-positive OPC response in the early phase after stroke is exaggerated." (PMID 31447640, 2019). "We have previously demonstrated that blocking the PDGF-CC/PDGF receptor alpha (PDGFRα) axis resulted in reduction of stroke volume and cerebrovascular permeability after experimentally induced stroke." (PMID 30021009, 2018). "Recent work has suggested tPA regulation of neurovascular barrier integrity, mediated via platelet derived growth factor (PDGF)-C/PDGF receptor-α (PDGFRα) signaling, as a possible molecular mechanism affecting the outcome of stroke." (PMID 26648843, 2015). "Importantly, PDGFRα inhibition was effective in improving functional recovery even when initiated 24 hours after stroke, which suggests opportunities for later treatment by targeting the PDGF pathway." (PMID 40026253, 2025). "Moreover, the number of APC+-OLs in the CC of the IBZ and the number of PDGFRα+-OPCs in the cortex of the IBZ of ABCA−B/−B-T2DM stroke mice were also reduced (p < 0.05, n = 9/group)." (PMID 35572941, 2022). "We firstly determined the phosphorylation of PDGFRα from the brain tissue of embolic stroke rats." (PMID 29850586, 2018). "To determine if DIO impairs OPC differentiation after stroke, we compared PDGFRα+ OPC and GST-π+ mature oligodendrocyte cell counts in three regions of interest spanning the ischemic white matter lesion at 28 days post-stroke." (PMID 36543124, 2022). "Consistent with our previous results, the present data show that the numbers of APC+-OLs and PDGFRα+-OPCs as well as APC+/BrdU+-OLs and PDGFRα+/BrdU+-OPCs in the IBZ of ipsilateral brain in ABCA1-B/-B vehicle stroke mice significantly decreased compared with those in ABCA1fl/fl vehicle stroke mice." (PMID 32575457, 2020). "Previously, we demonstrated that during stroke tPA acting on the parenchymal side of the neurovascular unit (NVU) can increase blood–brain barrier (BBB) permeability and ICH through activation of latent platelet-derived growth factor-CC (PDGF-CC) and signaling by the PDGF receptor-α (PDGFRα)." (PMID 28725968, 2017). "Stroke in the diabetic mice showed more NG2-positive cells than did stroke in the nondiabetic mice 21 d after ET-1 injection in the hippocampal CA1 region, but not PDGFRα." (PMID 36615583, 2023).
gastric cancer (16 papers, 2012 to 2025). A primary or metastatic malignant neoplasm involving the stomach. "Similar to U373 cells, manipulation of the activity of AKT1-CREB signaling by ectopic expression of PTEN led to decreased expression of PDGFRα in HGC-27 (a Pten-deficient gastric cancer cell line) cells, and depletion of PDGFRα attenuated the proliferation of HGC-27 cells." (PMID 33568640, 2021). "The relative expression of PDGFRα and PDGFRβ in gastric cancer cells was up-regulated with increasing LOX and downregulated with increasing BAPN (P < 0.05)." (PMID 38434983, 2024). "The relative expression of PDGFRα and PDGFRβ in gastric cancer cells increased with increasing LOX concentration but decreased with increasing BAPN concentration." (PMID 38434983, 2024). "Aberrant activation of PDGFRA has been reported in gastrointestinal mesenchymal tumors, glioma tumors, and gastric cancer." (PMID 39518984, 2024). "However, in recent gastric cancer research, studies have demonstrated that targeting both PDGFRA and PDGFRB in the tumor stroma can reverse the immunosuppressive microenvironment, leading to improved effectiveness of immune checkpoint inhibitors (ICIs)." (PMID 37568781, 2023). "With inhibition of PDGFRα and PDGFRβ using AG1295 or AG1296, VM formation in gastric cancer cells decreased (P <0.05), but the number of VM structures increased while LOX was added (P < 0.05)." (PMID 38434983, 2024). "In gastric cancer tissues, Gαi1 immunoprecipitated with multiple RTKs (EGFR, PDGFRα and FGFR) as well as the adapter protein Gab1, mediating downstream Akt-mTOR activation." (PMID 38049415, 2023). "Yan reported that KIT and PDGFRA mutation analysis of gastric tumors, background gastric mucosa, and GIST in 15 cases, wherein gastric GIST was accidentally found in surgical specimens operated for gastric cancer, showed no genetic association." (PMID 33512639, 2021).